CHD1L (chromodomain helicase DNA binding protein 1 like)
Description:
ATP-dependent chromatin remodeler that mediates chromatin-remodeling following DNA damage. Recruited to DNA damage sites through interaction with poly-ADP-ribose: specifically recognizes and binds histones that are poly-ADP-ribosylated on serine residues in response to DNA damage. Poly-ADP-ribose-binding activates the ATP-dependent chromatin remodeler activity, thereby regulating chromatin during DNA repair. Catalyzes nucleosome sliding away from DNA breaks in an ATP-dependent manner. Chromatin remodeling activity promotes PARP2 removal from chromatin.
Synonyms: ALC1; CHDL
Tractability: Small molecule: a structure with a bound ligand is known. PROTAC: ubiquitination databases record sites on it; its protein half-life has been measured.
Target class: Enzyme; Hydrolase
Gene: Protein-coding gene on chromosome 1 (147,242,643 to 147,295,767, forward strand). Ensembl gene ENSG00000131778.
Subcellular location: Nucleus; Chromosome
Subcellular location (Human Protein Atlas): Nucleoplasm
Pathways (Reactome):
DNA Repair: Dual Incision in GG-NER; Formation of Incision Complex in GG-NER
Gene Ontology:
Molecular function: ATP hydrolysis activity; ATP-dependent chromatin remodeler activity; histone reader activity; nucleosome binding; nucleotide binding; poly-ADP-D-ribose modification-dependent protein binding; protein binding; DNA helicase activity; ATP binding
Biological process: chromatin remodeling; DNA damage response; DNA repair
Cellular component: chromosome; nucleoplasm; nucleus; site of double-strand break
Genetic constraint (gnomAD): Loss-of-function variants: 86 observed, 89.32 expected, observed/expected ratio (o/e) 0.96, 90% interval 0.81 to 1.15. The upper end of that interval is the gene's LOEUF score, 1.15, which puts it in group 5 of 6, group 1 being the genes least tolerant of losing a copy. Missense variants: 1,043 observed, 978.66 expected, observed/expected ratio (o/e) 1.07, 90% interval 1.01 to 1.12. Synonymous variants: 376 observed, 359.14 expected, observed/expected ratio (o/e) 1.05, 90% interval 0.96 to 1.14.
Gene-disease validity (ClinGen):
ClinGen rates the evidence that CHD1L causes each of these diseases.
congenital anomaly of kidney and urinary tract (autosomal dominant): Limited. A urinary system disease characterized by structural malformations in the kidney and/or urinary tract containing vesicoureteral reflux.
Homologues: Orthologues: macaque CHD1L (98% identical), chimpanzee CHD1L (96% identical), pig CHD1L (91% identical), dog CHD1L (90% identical), guinea pig CHD1L (89% identical), rat Chd1l (88% identical), mouse Chd1l (86% identical), rabbit CHD1L (85% identical), zebrafish chd1l (64% identical). Paralogues in human: CHD6 (30% identical), CHD7 (30% identical), CHD3 (30% identical), CHD5 (30% identical), CHD1 (29% identical), CHD4 (29% identical), CHD8 (29% identical), CHD2 (29% identical), CHD9 (29% identical), SMARCA1 (27% identical), SMARCA4 (27% identical), SMARCA5 (26% identical), and 18 more.
Diseases named in the same sentence as CHD1L in open-access papers:
CHD1L is named in the same sentence as 74 diseases in open-access papers, as found by Europe PMC text mining. Sharing a sentence is not in itself a finding about the gene and the disease. The quoted sentences say what the papers report.
hepatocellular carcinoma (22 papers, 2012 to 2025). A malignant tumor that arises from hepatocytes. "Chromodomain helicase/ATPase DNA binding protein 1-like gene (CHD1L) is a recently identified gene associated with malignant tumor progression and patient chemotherapy resistance in human hepatocellular carcinoma (HCC)." (PMID 30718500, 2019). "Recently, we reported that the chromodomain helicase DNA binding protein 1-like (CHD1L) gene is a putative oncogene mapped to chromosome 1q21 and it is associated with hepatocellular carcinoma (HCC) tumorigenesis." (PMID 23020525, 2012). "Functional experiments in hepatocellular carcinoma cells demonstrate that CHD1L overexpression blocks Nur77 translocation, inhibits cytochrome c release, and prevents caspase-9 and caspase-3 activation." (PMID 40442742, 2025). "Originally named Amplified in Liver Cancer 1 (ALC1), CHD1L is located on the 1q21 chromosomal region, which is the most amplified region in hepatocellular carcinoma." (PMID 40442742, 2025). "In hepatocellular carcinoma cells, knockdown of CHD1L induces apoptosis, as shown by increased Annexin V staining, mitochondrial membrane depolarization, and elevated levels of cleaved PARP and caspase-3." (PMID 40442742, 2025). "In hepatocellular carcinoma, CHD1L upregulation has been shown to accelerate mitotic exit to the extent that it causes chromosome mis-segregation and increases overall mutational burden." (PMID 40442742, 2025). "Growing evidences demonstrated that CHD1L was highly expressed in most types of malignancy including hepatocellular carcinoma, lung cancer, breast cancer, gastric cancer, colorectal cancer, bladder cancer, and ovarian cancer." (PMID 34654797, 2021). "Functional studies suggested that CHD1L plays an oncogenic role in the tumorigenesis of hepatocellular carcinoma 24, colorectal carcinoma 26 and other tumors through unleashed cell proliferation, G1/S transition and inhibition of apoptosis." (PMID 31956354, 2020). "Chromodomain helicase DNA binding protein 1-like (CHD1L) gene has been proposed to play an oncogenic role in human hepatocellular carcinoma." (PMID 32922205, 2020). "Chromodomain helicase/ATPase DNA binding protein 1-like gene (CHD1L) is a newly identified oncogene that we previously isolated from a frequently amplified region at chromosome 1q of human hepatocellular carcinoma (HCC)." (PMID 26360781, 2015). "In a previous study amplification of CHD1L at the protein level was detected in most hepatocellular carcinomas (HCCs); and CHD1L-transfected cells were shown to possess a strong oncogenic ability." (PMID 25371726, 2014). "CHD1L protein over-expression in primary hepatocellular carcinoma is correlated with enhanced apoptosis inhibition, reduced chemosensitivity and shortened patient survival." (PMID 25153161, 2014). "Chromodomain helicase/ATPase DNA binding protein 1-like gene (CHD1L) is a recently identified oncogene that is frequently amplified in hepatocellular carcinoma (HCC)." (PMID 24359616, 2013). "Since CHD1L gene was isolated from the amplicon of Chr1q21 in tumors, the functional studies point to the oncogenic role of CHD1L in solid tumors, particularly in hepatocellular carcinoma." (PMID 24359616, 2013). "In hepatocellular carcinoma chromo-domain helicase/ATPase DNA binding protein 1-like gene (CHD1L) was frequently amplified." (PMID 23991421, 2013). "Functional studies of CHD1L in hepatocellular carcinoma and other tumors strongly suggested that its oncogenic role in tumorigenesis is through unleashed cell proliferation, G1/S transition and inhibition of apoptosis." (PMID 24359616, 2013). "Our recent studies suggested that the chromodomain helicase DNA binding protein 1-like (CHD1L) gene plays an oncogenic role in human hepatocellular carcinoma." (PMID 23020525, 2012). "CHD1L enhances hepatocellular carcinoma by modulating the ZKSCAN3-mediated autophagy process." (PMID 37691108, 2023).
hepatocellular carcinoma (continued). "CHD1L is an oncogene in several cancer types, particularly in hepatocellular carcinoma." (PMID 33644029, 2020). "Recently, intensive evidence demonstrated that CHD1L was highly expressed in most types of malignancy, like hepatocellular carcinoma (HCC), breast cancer, lung cancer, ovarian cancer, or colon cancer." (PMID 37691108, 2023). "Chromodomain helicase/adenosine triphosphatase DNA-binding protein 1-like gene (CHD1L) is originally verified in human hepatocellular carcinoma cells (HCC) and its oncogenic roles have been characterized in previous studies." (PMID 34588420, 2021). "Chromodomain helicase/ATPase DNA-binding protein 1-like gene (CHD1L) has been characterized to be a driver gene in hepatocellular carcinoma (HCC)." (PMID 34588420, 2021). "ARHGEF9 has been shown to play a role in tumor cell migration, invasion and metastasis by linking oncogene CHD1L and Cdc42 pathway in hepatocellular carcinoma (HCC)." (PMID 32503434, 2020). "A previous study demonstrated that CHD1L upregulates the expression of ARHGEF9, which subsequently activates Cdc42, causing filopodia formation, epithelial-mesenchymal transition (EMT), and finally promotes hepatocellular carcinoma cell invasion and metastasis." (PMID 32922205, 2020). "Amplification and overexpression of CHD1L is one of the most frequent genetic alterations in hepatocellular carcinoma (HCC)." (PMID 25575811, 2015). "CHD1L is a recently identified oncogene located at 1q21, a frequently amplified region in hepatocellular carcinoma (HCC)." (PMID 24359616, 2013). "CHD1L, the candidate oncogene, has been isolated from 1q21 amplicon and found frequently amplified in hepatocellular carcinoma (HCC)." (PMID 23020525, 2012). "CHD1L had the ability to bind to the promoter of ZKSCAN3, inhibiting its transcription and stimulating the hepatocellular carcinoma migration." (PMID 37033447, 2023). "ALC1/CHD1L is a macrodomain protein, a PAR-binding Snf2-like ATPase that has oncogenic activity and is frequently overexpressed in hepatocellular carcinoma (HCC) and other types of cancers." (PMID 34639169, 2021). "CHD1L (chromodomain helicase/ATPase DNA binding protein 1-like gene) has been demonstrated as an oncogene in hepatocellular carcinoma (HCC), however, the role of CHD1L in non-small-cell lung cancer (NSCLC) tumorigenesis hasn't been elucidated." (PMID 26360781, 2015). "CHD1L is a recently identified oncogene localized at 1q21 in hepatocellular carcinoma (HCC)." (PMID 26599012, 2015). "Macro domain of CHD1L acts to interact with Nur77, while the CHD1L mutants lacking residues 600–897 cannot interact with Nur77 and prevents Nur77-mediated apoptosis of hepatocellular carcinoma." (PMID 33663617, 2021).
breast carcinoma (14 papers, 2014 to 2025). "While in breast cancer, presence of CHD1L expression was associated with higher Ki-67 index and HER2 amplification." (PMID 26360781, 2015). "Presence of CHD1L over-expression is probably associated with aggressive tumor biology in breast cancer." (PMID 25153161, 2014). "Interestingly, The CHD1L mutation found in NUGC3 cell line is a pathogenic (score 0.91) breast cancer somatic mutation (Genomic Mutation ID COSV63615250)." (PMID 38589664, 2024). "However, the underlying molecular mechanism of CHD1L in promoting invasion and metastasis of breast cancer is unclear." (PMID 26599012, 2015). "According to our results, immunohistochemical staining status of CHD1L expression might be useful as an additional biomarker to identify those breast cancer patients with increased risk of relapse." (PMID 25153161, 2014). "We have previously reported in breast cancer cell lines that the pharmacological inhibition of the CHD1L ATPase activity by OTI-611 traps CHD1L onto chromatin." (PMID 39684869, 2024). "Taken together, the literature reports by others and our results herein demonstrate that CHD1L functions as a master regulator of tumor cell survival in breast cancer and likely other cancers." (PMID 39201277, 2024). "The targeted inhibition of CHD1L’s oncogenic function by OTI-611 signifies an innovative therapeutic strategy for breast cancer and other cancers." (PMID 39201277, 2024). "In breast cancer, CHD1L promoted cell metastasis and invasion through the PI3K/AKT/ARK5/mTOR/MMP pathway." (PMID 33663617, 2021). "CHD1L promoted the invasion and metastasis of breast cancer cells via the PI3K/Akt/ARK5/mTOR/MMP signaling pathway." (PMID 26599012, 2015). "This study identified CHD1L as a potential anti-metastasis target for therapeutic intervention in breast cancer." (PMID 26599012, 2015). "Further studies are warranted to demonstrate the function of CHD1L in many breast cancer cell lines and another signal pathway that affects the invasion and metastasis of breast cancer." (PMID 26599012, 2015). "In animal experiments, downregulation of CHD1L inhibited the metastasis of breast cancer cells toward the SCID mice lung." (PMID 26599012, 2015). "Recently, CHD1L has also been reported as a novel biomarker for patients' prognosis in several types of solid tumor, including breast cancer, gastric cancer, colorectal cancer, bladder cancer and ovarian cancer." (PMID 26360781, 2015). "The level of CHD1L protein was higher in breast cancer tissues than that of their corresponding ANT tissues (right)." (PMID 26599012, 2015). "In the cell experiment, reduction of CHD1L inhibited the invasion and metastasis of breast cancer cells by mediating MMP-2 and MMP-9 expression." (PMID 26599012, 2015). "In summary, we showed that CHD1L levels were higher in breast cancer cells and that CHD1L promoted breast cancer cell migration, invasion, and metastasis." (PMID 26599012, 2015). "Further basic and translational studies are warranted to demonstrate the mechanisms how CHD1L promotes tumor development in breast cancer." (PMID 25153161, 2014). "The results showed that the levels of CHD1L mRNA were relatively higher in breast cancer cell lines when compared to MCF-10A, especially in MDA-MB-231 and LM2-4175." (PMID 25153161, 2014). "Clearly, further studies are warranted to demonstrate the oncogenic function of CHD1L in breast cancer and the mechanisms how CHD1L promotes the development and metastasis of breast cancer." (PMID 25153161, 2014). "Expression of the mRNA level of CHD1L was analyzed in one normal breast epithelial cell line and six breast cancer cell lines by using QRT-PCR." (PMID 25153161, 2014).
breast carcinoma (continued). "In vitro study indicated that relative mRNA expression level of CHD1L was higher in breast cancer cell lines, especially in MDA-MB-231 and LM2-4175, when compared to normal breast epithelial cell line." (PMID 25153161, 2014). "Presence of CHD1L over-expression was more likely to be found in young breast cancer patients (P = 0.011)." (PMID 25153161, 2014). "In this study, we examined the protein expression of CHD1L by IHC in a cohort of breast cancer tissues and also identified the correlation of clinicopathological factors, breast cancer subtypes, and prognostic significance." (PMID 25153161, 2014). "CHD1L is considered a cancer or prognostic biomarker, because its overexpression is usually associated with poor prognosis, such as in HCC, gastric cancer, bladder cancer, breast cancer, NSCLC, cholangiocarcinoma, and nasopharyngeal carcinoma." (PMID 33663617, 2021). "In addition, amplification of CHD1L has been observed in various solid tumors, including breast cancer, colorectal cancer, bladder cancer, nasopharyngeal cancer, and HCC." (PMID 29088777, 2017). "In addition, CHD1L has been reported as a novel prognostic biomarker in several types of solid tumors, including prostate cancer, lung cancer, breast cancer, gastric cancer, colorectal cancer, bladder cancer, nasopharyngeal carcinoma, and ovarian cancer." (PMID 29088777, 2017). "However, CHD1L affects the invasion and metastasis of breast cancer via several signal pathways both in vitro and in vivo." (PMID 26599012, 2015). "CHD1L promoted invasion and metastasis of breast cancer cells." (PMID 26599012, 2015). "CHD1L can promote the metastasis of human breast cancer cells in the lungs of SCID mice." (PMID 26599012, 2015). "Therefore, MMP-2 and MMP-9 are key factors in CHD1L that promote invasiveness of breast cancer cells." (PMID 26599012, 2015). "The results demonstrated the potential function of CHD1L in promoting breast cancer metastasis." (PMID 26599012, 2015). "In this study, CHD1L was evidently upregulated in breast cancer tissues." (PMID 26599012, 2015). "CHD1L can promote invasion and metastasis of breast cancer cells." (PMID 26599012, 2015). "Presence of CHD1L over-expression might be a novel prognostic biomarker for patients with breast cancer." (PMID 25153161, 2014). "Also, quantitative real-time polymerase chain reaction (QRT-PCR) was employed to evaluate the mRNA level expression of CHD1L in six breast cancer cell lines." (PMID 25153161, 2014). "The expression level of CHD1L is relatively higher in breast cancer cell lines than in MCF-10A, the normal breast epithelial cell line which suggested that CHD1L might have an oncogenic ability." (PMID 25153161, 2014). "In our study, presence of CHD1L over-expression was found in 48.6% of the breast cancer patients." (PMID 25153161, 2014). "We also demonstrated that presence of CHD1L over-expression was associated with younger age, higher tumor grade, HER2 over-expression/amplification, and higher Ki-67 labeling index, which are all prognostic factors of unfavorable breast cancer biology." (PMID 25153161, 2014). "However, CHD1L protein status or mRNA expression in breast cancer and its clinical significance remain obscure." (PMID 25153161, 2014). "Thus, our study suggests that CHD1L could be a useful marker to predict tumor progression and a potential target for breast cancer therapy." (PMID 26599012, 2015). "CHD1L status might be a novel prognostic biomarker for patients with breast cancer." (PMID 25153161, 2014). "Since it has been reported that patients with mesenchymal-like breast cancer had a worse outcome, our results in vitro somehow confirmed that CHD1L expression was related to an aggressive breast cancer biology and might also indicate the probability of CHD1L playing a role in EMT of breast cancer." (PMID 25153161, 2014).